VCAN (versican)
Diseases named in the same sentence as VCAN in open-access papers (continued):
Sharing a sentence is not in itself a finding about the gene and the disease.
cancer (continued). "On the other hand, the hyaluronan and VCAN‐rich matrix inhibits the spreading and migration of immune cells, protecting cancer cells from immune responses." (PMID 40542654, 2025). "In cancer, versican, a member of the proteoglycan family, impacts proliferation, survival, invasion, metastasis, and inflammation." (PMID 40098313, 2025). "As our findings demonstrated a significantly higher percentage of VCAN-detectable tumors in ER+ cancers compared to ER− cancers, there exists the possibility of a link between estrogen signaling and VCAN accumulation." (PMID 40361362, 2025). "Versican is one of the major CSPGs highly expressed in cancer cell types such as osteosarcoma, testicular tumors, breast, pancreatic and colon cancer." (PMID 39334952, 2024). "Cell surface CD44 and subsequently assembled HA/VCAN aggregates can assist cancer cells in establishing polarised pericellular sheaths, thereby augmenting their motility." (PMID 38791985, 2024). "VCAN can be synthesised by cancer cells, ECs, and adjacent fibroblast cells, leading to an accumulation of VCAN in the ECM during the angiogenic process." (PMID 38791985, 2024). "In various diseases, including cardiovascular, pulmonary, autoimmune, and cancer, PGs such as versican and HA increase their expression in the ECM together with tumor necrosis factor-stimulated gene 6 (TSG-6) and inter-alpha trypsin inhibitor (IαI)." (PMID 39334952, 2024). "Certain HAIMs, including CD44, TSG-6, LYVE-1, RHAMM, HAPLN3, NCAN, and VCAN, can facilitate the proliferation of cancer cells." (PMID 38791985, 2024). "VCAN was identified as one of the potential key genes altered through early PSC cancer cell crosstalk, and further studies investigating the role of VCAN in PDA initiation and progression are needed." (PMID 39098880, 2024). "Research has shown that the VCAN gene is negatively regulated by methylation, leading to its high expression in cancer tissues." (PMID 39132501, 2024). "Experimental investigations have demonstrated that VCAN can enhance the motility of cancer cells and metastasis." (PMID 38791985, 2024). "The analysis of VCAN expression and VCAN PPI networks in KPC cells would have helped to gain a deeper insight into the complex interactions of cancer and stromal cells." (PMID 39098880, 2024). "Several studies have established the foundation for understanding the regulatory mechanisms that control versican expression in normal primary cell cultures and in carcinoma-derived cell lines." (PMID 39400584, 2024). "Studies in carcinoma-derived cell lines also indicate a role for PKB signaling in the control of versican expression." (PMID 39400584, 2024). "Versican expression is regulated by transcriptional mechanisms in various primary smooth muscle cell cultures and carcinoma-derived cell lines." (PMID 39400584, 2024). "Of these, PI3K and MAPK are known to regulate versican expression in smooth muscle cells and in carcinoma cell lines." (PMID 39400584, 2024). "In conclusion, KRAS-mutant cancers rely on host IL-1β, which they elicit from host macrophages via secretory versican that activates myeloid IKKβ." (PMID 36980752, 2023). "These collective findings support VCAN regulating numerous biological processes in cancers through diverse molecular mechanisms; however, the regulatory mechanisms require further investigation." (PMID 37461061, 2023). "A study using a mouse mammary tumor virus-polyoma middle T-antigen (MMTV-PyMT)-induced cancer model also demonstrated that high expression of VCAN promotes cancer cell metastasis to the lung in a TGF-β-dependent manner." (PMID 37108649, 2023). "Versican inhibits cancer cell attachment to stromal matrix, thereby facilitating cancer cell migration and invasion." (PMID 37784035, 2023). "Generalized expression of versican has been observed in a wide range of malignant tumors, including glioma, liver tumors, and lung tumors, as well as breast cancer, prostate tumors, stomach tumors, and bowel tumors." (PMID 37259101, 2023).
cancer (continued). "The expression of VCAN was also found to be significantly higher in the stage 3-4 group compared to the stage 1-2 group (p < 0.001), implying a correlation between VCAN expression and cancer stage." (PMID 37108649, 2023). "A cancer spheroid formation model of ovarian cancer confirmed the role of CAFs in influencing collagen type I, particularly by expressing versican, which promoted cancer invasiveness via the TGFβ pathway." (PMID 36793444, 2023). "Cancer cells have been identified as a prominent source of secreted versican in several cancer types." (PMID 37259101, 2023). "The results showed that the expression of ACAN and VCAN was significantly higher in cancer patients than in normal patients (p < 0.01)." (PMID 37108649, 2023). "The 5 members of the M0-ECM signature, FN1, VCAN, COL11A1, SFRP2, and MXRA5, have been associated with cancer progression, through markers of prognosis or the process of metastasis." (PMID 37188691, 2023). "We investigated the impact of suppressing VCAN in cancer cells on cell proliferation, as cell proliferation affects instrument data." (PMID 37108649, 2023). "High VCAN mRNA expression also portended poor survival in a number of human cancers from the KMplot pan-cancer RNAseq dataset." (PMID 36980752, 2023). "Versican (VCAN), also known as extracellular matrix proteoglycan 2, has been suggested as a potential biomarker in cancers." (PMID 37108649, 2023). "VCAN improves cancer cell survival, proliferation, migration, invasion, angiogenesis, treatment resistance, and metastasis in vitro and in vivo." (PMID 35804967, 2022). "Increasing evidence has revealed an important role of versican (VCAN) on various aspects of cancer progression." (PMID 36203562, 2022). "Our finding that CSGALNACT1 and VCAN expression levels in FLC are most similar to that of CCA suggests potential mechanistic parallels between the two cancer types in terms of fibrosis." (PMID 36923282, 2022). "As mentioned in this article, the expression of VCAN is increased in many cancers, including HCC, which is significantly related to the poor prognosis of patients with HCC." (PMID 35812745, 2022). "We found in this study that the levels of VCAN are upregulated in FLC more than in any other cancer type for which expression data are publicly available through TCGA." (PMID 36923282, 2022). "Increasing studies have shown VCAN is involved in various aspects of cancer progression, including cell proliferation, metastasis, and angiogenesis." (PMID 36203562, 2022). "Additional studies have demonstrated using VCAN-negative QRsP11 fibrosarcoma cells that VCAN is an important molecule in functional ECM and maintenance of cancer-associated fibroblasts." (PMID 35812745, 2022). "Recently, several studies have demonstrated that abnormal expression of VCAN was found in various cancer types such as prostate, breast, gastric, colorectal, ovarian, pancreatic, laryngeal, and testicular tumors." (PMID 33604385, 2021). "As with other ECM proteins, versican has pro- and anti-inflammatory properties, making it a key player in cancer development." (PMID 33466303, 2021). "Our histopathological evidence has shown that COL12A1 and FN1 are expressed from stromal cells, THBS2, and VCAN from stromal and cancer cells, while ITGA2, LAMB3, and LAMC2 are expressed solely from the cancer cells." (PMID 34007003, 2021). "Proteolysis of versican has been associated with CD8+ T cell migration in inflammatory diseases and cancer." (PMID 34527586, 2021). "The functional roles for versican in cancer are broad, including impacting proliferation, survival, invasion, metastasis, and inflammation." (PMID 34527586, 2021). "In cancer tissues, versican appears to be expressed mostly in the V0 and V1 isoforms, and silencing of these isoforms has a direct effect on cancer progression, migration and invasion." (PMID 34527586, 2021).
cancer (continued). "Altered immune cell trafficking and polarisation of immune cell phenotype is a prominent feature of most cancers and several studies have identified a role for versican in these processes." (PMID 34527586, 2021). "VCAN had been found to affect the occurrence and development of a variety of cancers, but its research in GC tissue was still unclear." (PMID 33631054, 2021). "Versican, a member of the hyalectan family of large chondroitin sulfate PGs (CSPGs), has been proved to be overexpressed in many cancers." (PMID 34733848, 2021). "An increased level in the expression of stromal VCAN has also been previously reported; it was correlated with a poor prognosis in some types of cancers." (PMID 33604385, 2021). "Collagen is one of the main components of ECM, which participates in cancer fibrosis and structural formation of solid cancers together with matrix glycoproteins, such as FN, laminins, elastin, and versican." (PMID 34733848, 2021). "Myeloid cell-derived versican, a macrophage activator, facilitated cancer metastatic growth in lung cancer." (PMID 32825245, 2020). "We further showed that FOXA2 is a direct target of miR-590-3p, while Versican (VCAN), a proteoglycan commonly overexpressed in cancer, is transcriptionally inhibited by FOXA2." (PMID 32993038, 2020). "Infiltrating myeloid cells secrete versican which can also exhibit immunosuppressive activities in some cancers." (PMID 32265939, 2020). "The role of Versican in cell adhesion, migration, and proliferation has been extensively studied, and in cancer, stromal expression of VCAN was strongly correlated with disease recurrence." (PMID 30846786, 2019). "In cancer, versican has been identified as a modulator of cell adhesion, proliferation, apoptosis, angiogenesis, invasion, and metastasis." (PMID 31334111, 2019). "Versican has been established to be overexpressed in a number of cancers, including prostate, breast, malignant myeloma, glioblastoma, laryngeal, pancreatic ovarian, gastric, testicular germ-cell, and cervical cancer, as recently discussed." (PMID 31068944, 2019). "Carcinomas in mixed tumor, the most common histological type diagnosed in neoplasm of the mammary gland of dogs, were used to evaluate versican expression in in situ and invasive areas." (PMID 31334111, 2019). "Carcinomas in mixed tumors classified as histological grade 1 presented higher versican expression in invasive areas when compared to in situ areas (P < 0.001)." (PMID 31334111, 2019). "Versican expression is often correlated with high cell proliferation rates, particularly in cancer and has been shown to bind to the cell-cycle regulator Midkine." (PMID 30126423, 2018). "Versican, also known as chondroitin sulfate proteoglycan 2, a central component of cancer-related inflammation, is highly expressed in metastatic bladder carcinomas and its overexpression is correlated with poor survival." (PMID 29207682, 2017). "Different studies show a strong relation between the expression of versican and a more aggressive and metastatic behavior in different cancer models." (PMID 29212223, 2017). "The HRO data set documented gains of STC2 in 8 HRO cancer tissues, of which 5 harboured gains of VCAN as well." (PMID 28486536, 2017). "Versican is thought to play a role in the formation of an anti-adhesive ECM that would support cancer cell growth and metastasis, and to stimulate production of pro-inflammatory cytokines by monocytes." (PMID 28481899, 2017). "Next we examined the V0 and V1 isoforms of versican, the main isoforms expressed among different cancer types, in TSCC tissues." (PMID 28035060, 2017). "Leptin and versican are secreted by white adipose, located in whole body, and can in an endocrine, paracrine and autocrine manner, promote cancer proliferation and survival." (PMID 29212223, 2017).
cancer (continued). "Versican is an ECM component contained in the supepicardial space that promotes cell invasion in some cancer cells (reviewed) and is required for endocardial cushion formation and subsequent EMT." (PMID 27505173, 2016). "We have previously shown an increased versican expression in stroma adjacent to invasive areas in canine carcinomas in mixed mammary gland tumors." (PMID 27490467, 2016). "A recent publication has clearly shown that through activation of TLR2 and TNF-alpha, versican can be accelerated to offer an appropriate environment for cancer cells to survive and pursue a metastatic spread." (PMID 25859560, 2015). "LOX-mediated cross-linking of collagen IV recruits CD11b+ BMDC to the metastatic niche in the lungs, and these CD11b+ cells further remodel the ECM into a favorable home for extravasating cancer cells, e.g., by laying down the proteoglycan versican." (PMID 26539408, 2015). "Versican is highly expressed in other chronic conditions in which active tissue remodeling is present, such as cancers, lung and airway inflammation, and kidney disease, among others." (PMID 26176948, 2015). "Versican, a large extracellular matrix proteoglycan, can promote cancer metastasis through facilitating cell proliferation, adhesion, migration and angiogenesis." (PMID 26515726, 2015). "Various studies have demonstrated increased stromal versican expression in tumors compared with normal tissue, such as in cancer of prostate, breast, colon, pancreas and ovary." (PMID 25593993, 2014). "Versican has been suggested to contribute to HA fragment activation of macrophages, and enhanced cancer metastasis through induction of the hyaluronidases." (PMID 24653726, 2014). "The core iCAMP gene set reproduces many well-established genes that are aberrantly expressed in cancer tissue, such as VCAN and KPNA2." (PMID 23536776, 2013). "It is V0 and V1, which are the predominant versican isoforms in stroma tissues of most cancers, while V2 expression seems to be restricted to the central nervous tissue." (PMID 23024773, 2012). "The particular activation or inhibition of downstream EGFR signaling appears to influence cancer cell apoptotic responses to versican mediated effects and appear variably modulated dependant on chemotherapeutic drug or EGFR inhibitor delivered." (PMID 22096483, 2011). "It is of note that previous studies also observed the strong presence of lumican and versican in cancer cells." (PMID 22132114, 2011). "Matrix proteoglycans versican and decorin are frequently over-expressed in various malignancies and are differently involved in the progression of cancer." (PMID 21791066, 2011). "In that study, they further showed that ligation of TLR2 by versican elicits the production of proinflammatory cytokines, providing a positive link between inflammation and cancer metastasis." (PMID 24212952, 2011). "In the central areas of malignant tumors, the staining was generally strong for both decorin and versican." (PMID 21791066, 2011). "Several studies have demonstrated abnormal expression of the matrix-secreted proteoglycans versican and decorin in various cancer types such as prostate, breast, gastric, colorectal, ovarian, pancreatic, laryngeal and testicular tumors." (PMID 21791066, 2011). "The expression of decorin and versican differed greatly in carcinomas with increased MD and carcinomas with MAMCs." (PMID 21791066, 2011). "In contrast, the expression of versican was significantly higher only in carcinomas showing increased MD and MAMCs compared to normal tissues with identical mammographic findings." (PMID 21791066, 2011). "A greater viability of cancer cells was observed in low serum and serum-free conditions in the presence of versican G3." (PMID 17662123, 2007). "Additionally, we evaluate the presence of VCAN- and αSMA-expressing fibroblasts as markers of subclinical inflammation in the intestine of patients who have developed cancer." (PMID 39980836, 2025).
cancer (continued). "Similarly, ER− cancers with undetectable VCAN contained significantly more intraepithelial CD8+ T cells (6.5 vs. 37.1, p = 0.022)." (PMID 40361362, 2025). "In particular, VCAN has shown significant oncogenic features in multiple cancer types." (PMID 40202958, 2025). "VCAN could sustain cancer progression either by having a direct impact on the cancer cell phenotype or by influencing the TME." (PMID 39501160, 2024). "Increased VCAN expression has also been observed in malignant tumors." (PMID 39205715, 2024). "The cancer cells were immunohistochemically positive for vascular endothelial growth factor and platelet-derived growth factor, whereas the thickened intima of the pulmonary arteries was positive for versican (VCAN)." (PMID 39205715, 2024). "In addition, since early diagnosis of metastasis is key to effective cancer therapy, VCAN can serve as a biomarker of metastasis." (PMID 36980752, 2023). "Additionally, VCAN RNA expression was observed to increase progressively with the advancement of cancer stage." (PMID 37108649, 2023). "Interestingly, VCAN and IKBKB alterations (mostly missense mutations) each occur in 5% of all cancer patients and are significantly mutually enriched (VCAN in KRAS and IKBKB in VCAN mutations) suggesting mutual addiction." (PMID 36980752, 2023). "ADAMTS 9 degrades aggrecan and versican in cancer cells, which are important components of its ECM." (PMID 36982551, 2023). "Therefore, VCAN, TN-C, and thrombospondin are pan-cancer EVP markers and also ECM components that can discriminate tumors from adjacent tissues with high sensitivity and specificity." (PMID 37350937, 2023). "However, there are few reports on the exploration of VCAN in cancer patients and its interaction with the immune microenvironment." (PMID 37108649, 2023). "Hence, VCAN-IKKβ-mediated addiction of KRASMUT cancers to host IL-1β can be used to indirectly target these tumors." (PMID 36980752, 2023). "Versican has also been shown to have a crucial role in the transformation and advancement of malignant tumors, with higher expression of versican in a range of malignant tumors being related with cancer recurrence and poor prognosis." (PMID 37259101, 2023). "Therefore, the pathological significance and signaling processes mediated by VCAN differ among different cancer cells." (PMID 37108649, 2023). "The contribution of VCAN to cancer progression is controversial." (PMID 35454809, 2022). "Thus, the regulation of G1 and G3 versican levels by proteases is an important factor in cancer cell motility and metastasis." (PMID 36338393, 2022). "Next, we sought to compare the expression of CSGALNACT1 and VCAN in FLC with other cancer types." (PMID 36923282, 2022). "Moreover, we also explored the relationship between VCAN expression and clinical outcome in human pan-cancer." (PMID 36203562, 2022). "Therefore, in the development and progression of HCC, VCAN is likely to interact with the microtubule structure to promote cancer." (PMID 35812745, 2022). "Moreover, VCAN has been confirmed to display a close relationship to the survival, development and recurrence of numerous malignant tumors." (PMID 36523602, 2022). "VCAN is an extracellular matrix component connected to a variety of cancers, and this gene may be used as a treatment or biomarker for RCC." (PMID 36314741, 2022). "The results are correlated with those of previous studies, such as the increased Versican (CSPG) expression shown in poorly differentiated tumors versus moderately differentiated carcinomas and Versican being an independent predictor of progression in patients with early stage cancer." (PMID 36230789, 2022). "Some studies reveal that VCAN plays an important role in various cancers." (PMID 33604385, 2021).